SNRPN (small nuclear ribonucleoprotein polypeptide N)
Diseases named in the same sentence as SNRPN in open-access papers (continued):
Sharing a sentence is not in itself a finding about the gene and the disease.
colorectal cancer (2 papers, 2011 to 2020). A primary or metastatic malignant neoplasm that affects the colon or rectum. "Knocking down SNRPN blocked the cell cycle at the G2/M phase transition and promoted tumor cell apoptosis, inhibiting the progression of colorectal cancer." (PMID 33224876, 2020). "In this study, SNRPN was highly expressed in colorectal cancer tissues and involved in the progression of this disease." (PMID 33224876, 2020). "Immunohistochemistry analysis of 1,310 colorectal cancer tissue samples showed that SNRPN highly expressed in cancer tissues than in adjacent tissues and was mainly localized in the nucleus." (PMID 33224876, 2020). "The present study provides important evidence of the axis of E2F8/SNRPN in colorectal cancer." (PMID 33224876, 2020). "To explore the up-steam of SNRPN, we found by luciferase reporter assay and chromosomal immunoprecipitation assay that E2F8 was a transcriptional regulator up-steam of SNRPN in colorectal cancer." (PMID 33224876, 2020).
fragile X syndrome (2 papers, 2015 to 2022). A genetic syndrome caused by mutations in the FMR1 gene which is responsible for the expression of the fragile X mental retardation 1 protein. "It is important to also note that quantitative analysis using MS-QMA was initially developed for newborn screening of fragile X syndrome in both sexes, targeting FMR1 promoter methylation, but was modified to also detect SNRPN promoter methylation in this study." (PMID 34982160, 2022).
gastric cancer (2 papers, 2020). A primary or metastatic malignant neoplasm involving the stomach. "In gastric cancer, SNRPN acts as a novel hyper-methylated gene with corresponding reduced expression levels compared with intestinal metaplasia." (PMID 33224876, 2020). "Statistical analysis showed that the TE, BAE, and MAE scores of imprinted genes GNAS, GRB10, and SNRPN were significantly increased in malignant samples for almost all ten cancer types (p < 0.01), with the only exception of SNRPN in gastric cancer." (PMID 32448196, 2020). "One particular exception is for the SNRPN gene expression in gastric cancer." (PMID 32448196, 2020).
germ cell tumor (2 papers, 2015 to 2020). A benign or malignant, gonadal or extragonadal neoplasm that originates from germ cells. "SNRPN methylation patterns in germ cell tumors have been reported to reflect primordial germ cell development." (PMID 25571951, 2015). "For example, SNRPN methylation patterns in germ cell tumors have been reported to reflect primordial germ cell development." (PMID 25571951, 2015). "In addition, hypomethylation of small nuclear ribonucleoprotein polypeptide N (SNRPN) gene in germ cell tumors was found to result in LOI." (PMID 32448196, 2020). "For example, various studies have demonstrated that SNRPN imprinting may be involved in the regulation of multiple types of cancer, including germ cell tumors (GCTs), acute myeloid leukemia and human uterine leiomyomas." (PMID 25571951, 2015).
glioma (2 papers, 2017 to 2019). A benign or malignant brain and spinal cord tumor that arises from glial cells (astrocytes, oligodendrocytes, ependymal cells). "We found that the high expression of SNRPN was correlated with better overall survival in all grade glioma patients (log-rank p-values < 0.05)." (PMID 32047515, 2019). "According to the abnormal protein level in high and low degree glioma, and mass spectra (MS) result after UCH-L5 overexpression, SNRPF, SNRPN and CKLF were as potential target genes of UCH-L5." (PMID 29371935, 2017). "It has been reported that the expression of SNRPN, SNRPF, and CKLF was abnormal in gliomas or other tumors." (PMID 29371935, 2017). "It has been reported that expression of SNRPN, SNRPF and CKLF is abnormal in glioma tissues." (PMID 29371935, 2017).
lung carcinoma (2 papers, 2021 to 2022). "Based on the elevated BAE, MAE and TE signatures observed for various cancers over benign lesions, we formulated a statistical malignancy prediction model and identified GNAS, GRB10 and SNRPN as effective diagnostic biomarkers in ten different cancer types, including lung cancer." (PMID 34906185, 2021). "A recent study identified aberrant allelic expression of both GNAS and HM13 at 20q11-13.32, as well as that of imprinted GRB10 at 7p12.1 and SNRPN 15q11.2 as useful biomarkers for lung cancer diagnosis." (PMID 36461044, 2022).
neurodevelopmental disabilities (2 papers, 2016 to 2020). "Small nuclear ribonucleoprotein polypeptide N (SNRPN) is an imprinted gene that plays an important role in various neurodevelopmental disabilities." (PMID 33224876, 2020). "The small nuclear ribonucleoprotein polypeptide N (SNRPN) gene, encoding the RNA-associated SmN protein, duplications or deletions of which are strongly associated with neurodevelopmental disabilities." (PMID 27430727, 2016).
Apnea (1 paper, 2024). Lack of breathing with no movement of the respiratory muscles and no exchange of air in the lungs. "Deletion outcomes vary by type (ORPHA ID: 98,793, ORPHA ID: 177,901), including type 2 genes such as SNORD116-1, SNRPN, SNORD115-1, OCA2, MAGEL2, NDN, and their role in the development of apnea." (PMID 38902749, 2024).
asthenozoospermia (1 paper, 2021). "The imprinted gene SNRPN has been found to be aberrantly methylated in asthenozoospermia and teratozoospermic smokers." (PMID 34368137, 2021). "Interestingly, imprinting errors at the SNRPN gene and IGF2-H19 have also been found in spermatozoa from asthenozoospermia patients and in ART-conceived human fetuses." (PMID 34368137, 2021).
autoimmune disorders (1 paper, 2024). "While SNRPN’s role in inflammation and sepsis is not well-characterized, alterations in SNRPN gene expression have been observed in certain autoimmune disorders." (PMID 38167131, 2024).
cerebrocostomandibular syndrome (1 paper, 2024). Cerebro-costo-mandibular syndrome (CCMS) is characterized at birth by posterior rib gaps and orofacial anomalies reminiscent of Pierre Robin syndrome that include palatal defects (short hard palate, absent soft palate, absent uvula), micrognathia and glossoptosis. "Similarly, SNRPN’s role in facial development has been documented, with its dysfunction associated with craniofacial anomalies like mandibulofacial dysostosis Guion-Almeida type and cerebrocostomandibular syndrome." (PMID 38903762, 2024).
Charcot-Marie-Tooth disease (1 paper, 2011). An inherited degenerative disorder involving the peripheral nerves. "Only eight of the events (all hotspot sites) associated with genomic disorders, including 22q11.2 deletion (TBX1, DiGeorge syndrome), 17p12 duplication (PMP22, Charcot-Marie-Tooth disease), and 15q11.2q13.1 duplication (UBE3A and SNRPN)." (PMID 22102821, 2011).
colorectal adenocarcinoma (1 paper, 2025). The most common type of colorectal carcinoma. "It was found that elevated expression of RPL31, CCT2, RPL17, and NUP85, as well as downregulation of NUP98, CDC37, DNM2, and SNRPN resulted from corresponding μ-ASOs treatment, correlating with improved survival in colorectal adenocarcinoma patients according to the TCGA database." (PMID 41373892, 2025).
cystic teratoma (1 paper, 2017). "There were varying degrees of hypermethylation of SNRPN and KvDMR in the presence of maternal uniparental disomy in both mature cystic teratomas." (PMID 28288660, 2017).
developmental delay (1 paper, 2025). "Recent studies confirm that duplications in this region, involving genes such as SNRPN, UBE3A, and GABRB3, are associated with neuronal hyperexcitability and synaptic alterations, resulting in autistic phenotypes with seizures and developmental delay." (PMID 40943430, 2025).
encephalopathies (1 paper, 2025). "The genes NDN, SNRPN, and UBE3A are known for their association with Prader–Willi syndrome; GABRB and GABRA5 are associated with encephalopathies; OCA2 and HERC2 are linked to skin pigmentation." (PMID 40149731, 2025).
hydrops (1 paper, 2010). "However, close inspection of individual profiles revealed that within the SCNT-hydrops group, there were individuals who showed aberrant hypo- or hypermethylation, particularly in the IGF2 exon 10 DMR, KCNQ1OT1, SNRPN and HAND1 regions." (PMID 20205951, 2010).
Hypertension (1 paper, 2017). The presence of chronic increased pressure in the systemic arterial system. "Three detected genes were recognized by previous studies, and the other 5 loci/genes (MAN1A1, LMO3, NPAP1/SNRPN, DNAL4, and RNA5SP455/KRT8P5) were novel findings, which had no strong main effect on hypertension and could not be easily identified by single-locus genome-wide studies." (PMID 28642868, 2017).
leukemia (1 paper, 2012). A malignant (clonal) hematologic disorder, involving hematopoietic stem cells and characterized by the presence of primitive or atypical myeloid or lymphoid cells in the bone marrow and the blood. "SNRPN (small nucleolar polypeptide) is an imprinted gene that is methylated in leukemias." (PMID 22429919, 2012).
medulloblastoma (1 paper, 2015). A malignant, invasive embryonal neoplasm arising from the cerebellum. "The results raise the question of the underlying mechanism of SNRPN regulation of the medulloblastoma cell cycle." (PMID 25571951, 2015). "Knockdown of SNRPN was demonstrated to significantly inhibit medulloblastoma cell growth and induce G2/M phase arrest in vitro." (PMID 25571951, 2015). "Altogether, to the best of our knowledge, this is the first study to report that SNRPN exerts a key role in medulloblastoma cell growth." (PMID 25571951, 2015). "In the present study, to analyze the role of SNRPN in medulloblastoma, the effect of SNRPN on cell growth was investigated in vitro using the Daoy human medulloblastoma cell line." (PMID 25571951, 2015). "Knockdown of SNRPN by infection with SNRPN-specific siRNA markedly inhibited the proliferation of the medulloblastoma cells." (PMID 25571951, 2015). "The SNRPN mRNA and protein levels in the two most widely used medulloblastoma cell lines, Daoy and D283Med, were measured." (PMID 25571951, 2015). "In the present study, the effect of SNRPN on cell growth was investigated in vitro using the Daoy human medulloblastoma cell line." (PMID 25571951, 2015). "In the present study, SNRPN, a polypeptide of a small nuclear ribonucleoprotein complex, was observed to exert an important role in cell growth in medulloblastoma cell lines." (PMID 25571951, 2015). "Knockdown of SNRPN markedly reduced the proliferation and colony formation ability of Daoy medulloblastoma cells." (PMID 25571951, 2015). "In order to investigate the role of SNRPN in medulloblastoma, Daoy cells were transfected with Lv that stably expressed SNRPN-specific siRNA (Lv-shSNRPN) and reporter gene GFP." (PMID 25571951, 2015). "In conclusion, to the best of our knowledge, this is the first study to define SNRPN as a functional mediator of medulloblastoma cell growth." (PMID 25571951, 2015). "The results indicate that SNRPN may be a potential novel target for the development of pharmacological therapeutics in human medulloblastoma." (PMID 25571951, 2015). "Knockdown of SNRPN may also impair the anchorage-independent growth of medulloblastoma cells." (PMID 25571951, 2015). "However, the role of SNRPN in human medulloblastoma remains unknown." (PMID 25571951, 2015).
melanoma (1 paper, 2023). A malignant, usually aggressive tumor composed of atypical, neoplastic melanocytes. "To describe NAGK–SNRPN complex variability in the cell body and process of the neuron, we observed the microtubule transport machinery of NAGK and SNRPN in a melanoma cell line model." (PMID 37511433, 2023). "To elucidate dynein-mediated microtubule transport, we used a melanoma cell line to observe the colocalization of NAGK or SNRPN protein transport with melanosome." (PMID 37511433, 2023).
placental disorders (1 paper, 2017). "We analyzed the mRNA expression of three imprinting genes SNRPN, PEG10 and MEST in physiological first, second and third trimester groups and placental disorders (preeclampsia and molar pregnancy) and JEG-3 cells (choriocarcinoma cell line)." (PMID 28098215, 2017). "This is the first study to show association of abnormal DNA and histone methylation at DMRs of SNRPN, PEG10 and MEST with the development of placental disorders." (PMID 28098215, 2017).
Prader-Willi-like syndrome (1 paper, 2024). "For example, MAGEL2 deletion has been associated with Prader-Willi-like syndrome (ORPHA ID:398,069), including a UPD case (ORPHA ID:98,754) with a role for the SNRPN, OCA2, MAGEL2, and NDN genes." (PMID 38902749, 2024).
psoriasis (1 paper, 2023). An autoimmune condition characterized by red, well-delineated plaques with silvery scales that are usually on the extensor surfaces and scalp. "And the result displayed that three hub genes (GNAS, AUC = 0.709; IGF2, AUC = 0.644; and SNRPN, AUC = 0.926) had a credible diagnostic value for psoriasis." (PMID 37935955, 2023). "We first identified three hub genes, including SNRPN, IGF2, and GNAS, which could be potential therapeutic targets of psoriasis and T2D." (PMID 37935955, 2023).
Sepsis (1 paper, 2024). Sepsis is defined as life-threatening organ dysfunction caused by a dysregulated host response to infection. "Additionally, compared to normal samples, SNRPN exhibited reduced expression in Pre-B cells (CD34−) and T cells of sepsis." (PMID 38167131, 2024).
teratoma (1 paper, 2019). A non-seminomatous germ cell tumor characterized by the presence of various tissues which correspond to the different germinal layers (endoderm, mesoderm, and ectoderm). "Hypermethylation of SNRPN increased as the cellular origin of the tumors advanced in oogenesis and was closely correlated in individual teratomas." (PMID 32047515, 2019).
Williams syndrome (1 paper, 2009). "Similarly, the frequency of SD cells in the samples from the Williams syndrome patients ranged from 12% to 31% for the SNRPN locus and from 29% to 51% for the RB1 locus with a mean of 23.4 ± 6.5% and 36.2 ± 6.7%, respectively." (PMID 19284877, 2009). "However, in the cell samples from the DGS/VCFS and the Williams syndrome patients, the frequency of SD cells for the imprinted SNRPN locus were significantly lower than the corresponding values for RB1 (P < 0.001 for the DGS/VCFS patients and P < 0.0002 for those with Williams syndrome)." (PMID 19284877, 2009).
cancer (19 papers, 2008 to 2025). A tumor composed of atypical neoplastic, often pleomorphic cells that invade other tissues. "In vitro studies in cancer cell lines showed that increased cell proliferation, metastatic capability, and cell cycle progression positively associate with SNRPN expression." (PMID 37575996, 2023). "We therefore selected GNAS, GRB10, and SNRPN genes as the more efficient cancer biomarkers for our diagnostic model." (PMID 32448196, 2020). "For this investigation, we focused on the expression status of three imprinted genes—GNAS, GRB10, and SNRPN known to be associated with cancer status." (PMID 32448196, 2020). "On the other hand, in samples V and Z derived from non-cancer patients, as well as samples Y, A, and C derived from cancer patients, the early replicating SNRPN allele was found in more than 75% of SD cells on the chromosome identified by a small CEN15 marker." (PMID 19109880, 2008). "The early replicating CEN15 allele in cancer cases A and C resided on the same homologous chromosome as the early replicating SNRPN allele." (PMID 19109880, 2008). "However, in PHA-stimulated peripheral blood lymphocytes of the cancer patients, the SNRPN gene exhibited a relaxation, almost a loss, leaving only remnants of its characteristic asynchronous pattern of replication." (PMID 19109880, 2008). "Such genes showed a lower proportion of monoallelic vs biallelic expression in cancer cell lines than some other imprinted genes, e.g., SNRPN, SGCE, NLRP2, H19, and ANO1." (PMID 40414875, 2025). "Small nuclear ribonucleoprotein polypeptide N (SNRPN), an snRNA, interacts with various RBPs to modulate RNA splicing processes, affecting gene expression patterns in diverse cancers." (PMID 40271197, 2025). "A diagnostic tool to distinguish 10 cancers by two or more positive genes of gene classes (GNAS, GRB10, and SNRPN)." (PMID 38812777, 2024). "The third gene, SNRPN, is considered a putative oncogene, due to prevalent gain-of-function alterations and duplications in cancer." (PMID 37575996, 2023). "To analyze the allelic expression of imprinted genes in cancer, we selected 5 imprinted genes GNAS, GRB10, SNRPN, IGF2, and IGF2R which were mostly reported to be associated with cancer." (PMID 32448196, 2020). "Using these results, imprinted genes GNAS, GRB10, and SNRPN were identified as the more efficient cancer biomarkers over IGF2 and IGF2R, specifically using our QCIGISH method." (PMID 32448196, 2020). "We further analyzed the expression of imprinted genes GNAS, GRB10, and SNRPN in 204 benign and 654 malignant samples across ten cancer types." (PMID 32448196, 2020). "For our study, all the GNAS, GRB10, and SNRPN genes shared a similar expression pattern in 753 cases of ten cancers." (PMID 32448196, 2020). "On the other hand, in cancer cases Y and J, the early replicating CEN15 and SNRPN alleles were assigned to different homologues (bars Y)." (PMID 19109880, 2008). "In contrast, the samples of the non-cancer patients were not affected by AZA, evidenced by the lack of difference, in the presence of AZA, between the cancer cases and the non-cancer cases in the SD values for SNRPN as well as for CEN15." (PMID 19109880, 2008). "Here, we show that AZA reinstated the asynchronous replication of SNRPN in cells of the cancer patients by re-establishing the advanced replication of the normally early replicating (paternal) allele." (PMID 19109880, 2008). "At the same time, the cells of the cancer-free urology patients exhibited the normal pattern of replication: high SD values for SNRPN and significantly lower values for CEN15." (PMID 19109880, 2008). "Differential methylation patterns of SNRPN have also been reported in multiple types of cancer." (PMID 33224876, 2020). "Previous studies have also shown that SNRPN abnormal imprinting may promote the occurrence of many cancers." (PMID 32693431, 2020). "To explore the biological function of SNRPN, we characterized it in cancer cells." (PMID 33224876, 2020).